RNU6-1323P (RNA, U6 small nuclear 1323, pseudogene)
Gene: Small nuclear RNA gene on chromosome X (116,850,839 to 116,850,945, reverse strand). Ensembl gene ENSG00000206752.
Homologues: Orthologues: chimpanzee U6 (94% identical), macaque U6 (90% identical), rabbit U6 (88% identical), mouse Gm22950 (87% identical), dog U6 (84% identical), guinea pig U6 (84% identical), rabbit U6 (79% identical). Paralogues in human: RNU6-20P (93% identical), RNU6-25P (93% identical), RNU6-1 (92% identical), RNU6-1072P (92% identical), RNU6-1316P (92% identical), RNU6-2 (92% identical), RNU6-29P (92% identical), RNU6-38P (92% identical), RNU6-3P (92% identical), RNU6-48P (92% identical), RNU6-4P (92% identical), RNU6-5P (92% identical), and 1289 more.